GLP1R (glucagon like peptide 1 receptor)
Diseases named in the same sentence as GLP1R in open-access papers (continued):
Sharing a sentence is not in itself a finding about the gene and the disease.
neuroendocrine tumors (7 papers, 2014 to 2025). "The binding affinity and specificity of [18F]exendin-4 used in this study to GLP-1R have been validated previously in neuroendocrine tumors and pancreatic β-cell tracking." (PMID 33414373, 2021). "Neuroendocrine tumors are well vascularized and express specific cell surface markers, such as somatostatin receptors and the glucagon-like peptide-1 receptor (GLP-1R)." (PMID 24528513, 2014). "Recent studies have discovered novel targets in neuroendocrine tumors, such as the glucose-dependent insulin-biophilic polypeptide receptor (GIPR), the same hormone receptor as GLP-1R." (PMID 37780209, 2023). "GLP-1R is highly expressed on insulinomas, gastrinomas, phaeochromocytomas, and other neuroendocrine tumors, and [Lys40(Ahx-DTPA-111In)NH2]-exendin-4, a radiolabelled GLP-1 analogue, is specifically internalized in GLP-1R-expressing tumor cells." (PMID 24528513, 2014). "Glucagon-like peptide 1 receptor agonists (GLP-1Ra) are a popular class of medication that has been shown to reduce cancer risk, but their effects on patients with neuroendocrine neoplasms (NENs) have not yet been studied." (PMID 40361517, 2025).
Osteopenia (7 papers, 2018 to 2025). Osteopenia is a term to define bone density that is not normal but also not as low as osteoporosis. "GLP1-R knockout mice showed densitometry-measured osteopenia and bone fragility and increased bone histomorphometry-evaluated resorption and osteoclastic activity." (PMID 31541189, 2019).
phaeochromocytomas (7 papers, 2013 to 2026). "This makes it unlikely that GLP-1R stimulation could cause the release of clinically significant amounts of insulin from a phaeochromocytoma." (PMID 41488993, 2026). "However, one cannot exclude that clonal expansion of cells containing both proteins could occur very rarely, greatly increasing the number of such cells, and cause GLP-1R-stimulated insulin release and hypoglycaemic episodes in phaeochromocytoma patients." (PMID 41488993, 2026). "To validate the transcription of GLP-1R in a larger cohort, we analysed a TCGA cohort of 182 phaeochromocytomas and paragangliomas." (PMID 41488993, 2026). "In 20 phaeochromocytomas, we performed sequential double staining with anti-insulin and anti-GLP-1R antibodies and, in selected cases, staining with anti-insulin alone." (PMID 41488993, 2026). "Most phaeochromocytomas contain tumour cells producing insulin, and about half of phaeochromocytomas contain tumour cells producing GLP-1R." (PMID 41488993, 2026). "A reasonable estimate based on the collective findings is that about half of phaeochromocytomas produce GLP-1R." (PMID 41488993, 2026). "Among those are insulin produced in some tumour cells in most phaeochromocytomas and GLP-1R found in some phaeochromocytomas." (PMID 41488993, 2026). "The number and proportion of phaeochromocytoma cells that contain insulin or GLP-1R were scored in all six tumours together and for each tumour separately." (PMID 41488993, 2026). "Most phaeochromocytomas produce insulin, and some produce glucagon-like peptide 1 receptor (GLP-1R)." (PMID 41488993, 2026). "The mechanism could be that GLP-1R stimulation induces differentiation of phaeochromocytoma cells, which may mean less aggressive tumours." (PMID 41488993, 2026). "GLP1R expression/protein has been found on phaeochromocytoma cells and tumours, but whether they function normally or if they are expressed on cells positive for anti-insulin staining is not known." (PMID 34170845, 2021). "Thus, cells synthesizing GLP-1R occur in many phaeochromocytomas." (PMID 41488993, 2026). "Thus, phaeochromocytomas may cause hypoglycaemia from insulin release also without stimulation of the GLP-1R." (PMID 41488993, 2026). "Normal adrenal medulla, where phaeochromocytomas originate, also does not stain for GLP-1R or insulin." (PMID 41488993, 2026).
acute coronary syndrome (6 papers, 2013 to 2026). Signs and symptoms related to acute ischemia of the myocardium secondary to coronary artery disease. "Our data propose that selectively blocking GLP-1R-mediated chronotropic effects via agonizing GABABR might expand GLP-1RA utility into acute coronary syndromes." (PMID 41244817, 2025).
alcohol (6 papers, 2015 to 2025). "The current study aimed to investigate the potential association of GLP1R rs10305420 and rs6923761 and GIPR rs1800437 with alcohol dependence, as well as alcohol-related comorbid psychosymptomatology." (PMID 35754710, 2022). "First, we report evidence and replication that genetic variation in GLP1R is associated with AUD and alcohol dependence in humans." (PMID 26080318, 2015). "In the preclinical study, a GLP-1R agonist was evaluated in a mouse model of alcohol dependence to demonstrate the role of GLP-1R for alcohol consumption." (PMID 26080318, 2015). "Regarding GLP-1, we observed an association between GLP1R rs6923761 GG genotype and Zung anxiety scores in healthy controls, but not between GLP1R rs10305420 and rs6923761 and alcohol dependence." (PMID 35754710, 2022). "Finally, GLP-1R agonism significantly reduced alcohol consumption in a mouse model of alcohol dependence." (PMID 26080318, 2015). "Finally, the preclinical study investigated GLP-1R agonism on alcohol consumption as a pharmacological validation of the role of GLP-1R in alcohol dependence." (PMID 26080318, 2015). "Specifically, we present five complementary studies, that is, four human genetic association studies investigating the genetics of GLP-1R in the context of AUD, and one preclinical study examining the role of GLP-1R agonism in a mouse model of alcohol dependence." (PMID 26080318, 2015). "Finally, we report that pharmacological GLP-1R agonism with AC3174 significantly reduced alcohol consumption in a mouse model of alcohol dependence." (PMID 26080318, 2015). "Finally, they investigated the impact of GLP-1R agonism on alcohol dependence in a mouse model." (PMID 35754710, 2022). "Consistent with our hypothesis and the results obtained in these human experiments, we found converging evidence in a mouse model of alcohol dependence where pharmacological GLP-1R agonism via an exendin-4 analog (AC3174) significantly reduced alcohol consumption." (PMID 26080318, 2015). "The combined GIPR/GLP1R relationships with NAFLD, liver enzymes (ALT, GGT), binge drinking, alcohol misuse, and food liking outcomes show consistent protective relationships across both loci, with estimates from the GIPR locus providing particularly robust evidence." (PMID 40931165, 2025). "We conducted a pilot study to investigate the role of GLP1R rs10305420 and rs6923761 and GIPR rs1800437 in alcohol dependence and related psychosymptomatology in a cohort of hospitalized alcohol-dependent patients, abstinent alcohol-dependent patients, and healthy individuals." (PMID 35754710, 2022).
cholangiocarcinoma (6 papers, 2013 to 2025). A carcinoma that arises from the intrahepatic biliary tree (intrahepatic cholangiocarcinoma) or from the junction, or adjacent to the junction, of the right and left hepatic ducts (hilar cholangiocarcinoma). "Glucagon-like peptide 1 receptor (GLP-1R) agonist is an emerging anti-diabetic medication whose effects on the risk and progression of cholangiocarcinoma (CCA) are controversial." (PMID 38877189, 2024). "For instance, GLP-1R agonists like liraglutide have been shown to slow the progression of cholangiocarcinoma by inhibiting cell migration and reducing tumor growth, despite the association of GLP-1R expression with poor histological grading in intrahepatic cholangiocarcinoma tissues." (PMID 39777709, 2025).
cholelithiasis (6 papers, 2016 to 2025). The presence of crystallized deposits forming in the gallbladder or biliary tree, primarily composed of cholesterol, bilirubin, and bile. "With the widespread use of glucagon-like peptide-1 receptor agonists (GLP-1 RAs) in managing diabetes and obesity, the occurrence of GLP-1 RA-induced cholecystitis and cholelithiasis has raised increasing concern among healthcare professionals." (PMID 40697657, 2025).
gastroparesis (6 papers, 2013 to 2025). Paralysis of the muscles of the stomach wall resulting in delayed emptying of the gastric contents into the small intestine. "The most reported adverse effects of GLP1R agonists are gastrointestinal; patients report increased emetic responses, as well as exacerbation of gastroparesis." (PMID 39007271, 2024).
Huntington disease (6 papers, 2012 to 2025). Huntington disease (HD) is a rare neurodegenerative disorder of the central nervous system characterized by unwanted choreatic movements, behavioral and psychiatric disturbances and dementia. "GLP-1R agonists may have the ability to ameliorate the progression of Huntington’s disease due to their neuroprotective effects." (PMID 39858999, 2024). "However, more studies are needed to confirm the role of GLP-1R agonists in the treatment of Huntington’s disease." (PMID 39858999, 2024).
Impaired glucose tolerance (6 papers, 2015 to 2024). An abnormal resistance to glucose, i.e., a reduction in the ability to maintain glucose levels in the blood stream within normal limits following oral or intravenous administration of glucose. "GLP-1R signaling plays a critical role in the maintenance of glucose homeostasis as deletion of the GLP-1R in mice results in impaired glucose tolerance and physiological levels of GLP-1 enhance meal-related insulin secretion in humans." (PMID 25852463, 2015).
ovarian carcinoma (6 papers, 2021 to 2025). A malignant neoplasm originating from the surface ovarian epithelium. "In ovarian cancer, high GLP1R expression was associated with significantly better survival (HR = 1.27, ogrank p = 0.14)." (PMID 39777709, 2025). "Preclinical studies have demonstrated that Ex-4 exhibits anti-tumor effects in human ovarian cancer cell lines SKOV-3 and CAOV-3 by activating the GLP-1R." (PMID 40140925, 2025). "Relevant preclinical studies have demonstrated that Ex-4, by acting on GLP-1R, inhibits the PI3K/Akt signaling pathway and increases the expression of Caspase-3 and E-cadherin, thereby promoting apoptosis in human ovarian cancer cells and reducing their metastasis." (PMID 40140925, 2025). "In addition, exenatide was shown to activate GLP-1R and inhibit the PI3K/AKT pathway to inhibit the growth, migration, and invasion of ovarian cancer cells, and promote cell apoptosis, thereby producing anticancer effects on diabetic patients with ovarian cancer." (PMID 34497589, 2021).
papillary thyroid cancer (6 papers, 2023 to 2026). "A study also reported that the rs1042044 C>A polymorphism may influence the risk of papillary thyroid cancer by affecting GLP-1R expression." (PMID 38096145, 2023). "Consistent with our findings, a previous study reported that GLP-1R expression in papillary thyroid carcinomas is negatively correlated with tumor multifocality." (PMID 39777709, 2025).
Thyroid neoplasms (6 papers, 2016 to 2026). "Moreover, a decreased incidence of prostate, bladder, and uterine neoplasm was observed in T2D patients with weight reduction difference while an increased incidence of thyroid neoplasm was found in glucagon-like peptide-1 receptor analog (GLP-1RA) users with weight reduction difference." (PMID 33424764, 2020).
Abdominal obesity (5 papers, 2021 to 2026). Excessive fat around the stomach and abdomen. "GLP-1R in EAT is related to fatty acid oxidation and white fat browning, and there may be a brown fat whitening transition in adipocyte hypertrophy and hyperplasia in EAT of abdominal obesity T2DM patients." (PMID 34825006, 2021).
bowel obstruction (5 papers, 2021 to 2026). "They avoid the adverse effects of surgery (malnutrition, post-prandial hypoglycaemia, bowel obstruction, etc.)and GLP1R agonists (gastrointestinal symptoms)." (PMID 34072172, 2021).
eating disorder (5 papers, 2017 to 2025). A broad group of psychological disorders with abnormal eating behaviors leading to physiological effects from overeating or insufficient food intake. "While GLP-1R agonists show promise for managing binge eating, there is concern about their misuse in populations with eating disorders, where their appetite-suppressing effects could exacerbate restrictive eating behaviors." (PMID 39715341, 2025).
injury (5 papers, 2017 to 2025). Damage inflicted on the body as the direct or indirect result of an external force, with or without disruption of structural continuity. "The following sections discuss the potential of GLP-1/GLP-1R induced mechanisms in the protection and/or prevention of both acute brain disorders like cerebral ischemia or brain injury, and chronic neurodegenerative diseases such as AD, PD, HD, and ALS." (PMID 28846606, 2017). "HI brain injury reduced mRNA and protein levels for phosphorylated PI3K and Akt, while treatment with both GLP1-R agonists normalised levels." (PMID 38783166, 2024).
migraine (5 papers, 2020 to 2025). "This pilot study provides the first preliminary clinical evidence supporting the use of liraglutide, a GLP‐1R agonist, for the preventive treatment of migraine." (PMID 40525593, 2025). "Future randomized controlled trials, with a comparator arm, are needed to confirm the effectiveness of GLP‐1R agonists in migraine prevention." (PMID 40525593, 2025). "We observed a significant reduction in the number of MHDs among patients receiving liraglutide, demonstrating that targeting the GLP‐1R may be an effective strategy for unresponsive migraine prevention." (PMID 40525593, 2025). "However, as an exploratory pilot study, these findings provide a foundation for larger‐scale trials aimed at further investigating the role of GLP‐1R agonists in migraine management." (PMID 40525593, 2025). "Therefore, this study investigates GLP‐1R agonists as a potential promising approach to alleviating migraine." (PMID 40542572, 2025). "Therefore, this was a hypothesis‐driven study exploring the potential of GLP‐1R agonists as a novel prophylactic treatment for migraine." (PMID 40525593, 2025). "By reducing ICP, GLP‐1R agonists might reduce CGRP release and central sensitization at the level of the trigeminal nucleus caudalis, contributing to their effectiveness in migraine prevention." (PMID 40525593, 2025). "If this finding was confirmed by randomized controlled trials on larger populations, GLP‐1R agonists might represent the first migraine treatment acting by preventing CGRP release rather than controlling its effects on pain pathways." (PMID 40525593, 2025). "The central hypothesis posits that if a deranged ICP control is the shared pathogenetic step between migraine and IIHWOP, responsible for their striking clinical and pathogenetic similarities, then GLP‐1R agonists should improve migraine frequency and intensity." (PMID 40525593, 2025).
morbid obesity (5 papers, 2012 to 2024). An excess of body weight, normally defined as an individual with a body mass index greater than 35 or a body weight greater than one hundred percent of ideal body weight. "In subjects with morbid obesity and T2D, GLP-1R expression in AT is of limited value to predict incretin response and does not play a role in metabolic outcomes such as insulin sensitivity improvement, T2D remission and weight loss after bariatric surgery." (PMID 31000783, 2019). "Interestingly, Vendell and colleagues reported that GLP-1R expression (mRNA, protein) is greatest in adipocytes isolated from patients with morbid obesity and in particular, IR." (PMID 26394161, 2016). "Moreover, GLP-1R expression in AT is not very useful in predicting incretin response in people with morbid obesity and T2D." (PMID 39201336, 2024).
muscle atrophy (5 papers, 2021 to 2026). The loss of muscle tissue due to inactivity or disease. "The current scoping review of extant literature aims to synthesize findings from studies assessing the therapeutic effects of GLP-1R agonists in the management of inflammatory myopathy and muscle atrophy." (PMID 38292961, 2023). "Studies about the therapeutic effects of GLP-1R agonists in the management of inflammatory myopathy and muscle atrophy are relatively limited, in part due to the research constraints of examining clinically rare diseases like IIM." (PMID 38292961, 2023). "Moreover, in the GC‐induced muscle atrophy model, GLP‐1R agonist inhibited the translocation of GC receptor into the nuclei." (PMID 35775116, 2022).
periodontitis (5 papers, 2020 to 2025). An acute or chronic inflammatory process that affects the tissues that surround and support the teeth. "Immune cells (macrophages/monocytes/lymphocytes) express GLP‐1R; chronic periodontitis shows upregulated NF‐κB; liraglutide reduces inflammatory infiltration and bone loss in ligature models." (PMID 41328144, 2025). "Our previous study found that the expression of GLP-1R was detected on hPDLCs, and LIRA could inhibit the expression of IL-6 and TNF-α on the experimental periodontitis." (PMID 35845316, 2022).
peripheral nerve injury (5 papers, 2015 to 2024). Injury to a peripheral nerve. "Lamiophlomis rotata, a Tibetan herb containing iridoid glycosides with GLP-1R agonist activity, blocked formalin-induced hyperalgesia, peripheral nerve injury- and bone cancer-induced mechanical allodynia." (PMID 38997662, 2024). "This study investigates the potential of liraglutide, a glucagon-like peptide-1 receptor agonist, in mitigating the consequences of peripheral nerve injury." (PMID 38248323, 2024). "Consistent with our data, the upregulation of GLP-1R in the spinal cord on activated microglia was also found after peripheral nerve injury." (PMID 34325647, 2021).
pulmonary fibrosis (5 papers, 2020 to 2025). Chronic progressive interstitial lung disorder characterized by the replacement of the lung tissue by connective tissue, leading to progressive dyspnea, respiratory failure, or right heart failure. "GLP1R agonist (liraglutide) was able to reverse pulmonary fibrosis in the bleomycin-induced rat model." (PMID 37221600, 2023). "The aim of the present study was to study the possible beneficial effects of the administration of the GLP-1R agonist, liraglutide, in the pathogenesis of the fibrotic process in an animal model of pulmonary fibrosis induced by bleomycin." (PMID 33093510, 2020).
venous thromboembolism (5 papers, 2024 to 2026). Occlusion of the lumen of a vein by a thrombus that has migrated from a distal site via the blood stream. "This case report emphasizes the need for venous thromboembolism risk assessment in patients starting on glucagon-like peptide 1 receptor agonists." (PMID 39734498, 2024). "Adequate risk assessments and close monitoring should be performed in patients initiating glucagon-like peptide 1 receptor agonists, particularly if they have risk factors for developing venous thromboembolism." (PMID 39734498, 2024).